MMP8 (matrix metallopeptidase 8)
Diseases named in the same sentence as MMP8 in open-access papers (continued):
Sharing a sentence is not in itself a finding about the gene and the disease.
Arthritis (17 papers, 2010 to 2025). Inflammation of a joint. "MMP-8 is associated with diverse inflammatory diseases such as neuroinflammation, multiple sclerosis, arthritis, and encephalomyelitis)." (PMID 36834565, 2023). "Arthritis was monitored until day 9 and the results confirmed those previously obtained - arthritis severity was significantly higher in Mmp8-deficient mice compared with control mice (P = 0.04 by repeated-measures one-way ANCOVA test)." (PMID 21190566, 2010). "Most were coincident in Mmp8-sufficient and Mmp8-deficient mice, and they can be grouped in functional categories that are congruent with current knowledge of arthritis mechanisms." (PMID 21190566, 2010). "In the present study we have therefore investigated the impact of Mmp8 deficiency in the induced arthritis using the K/BxN serum transfer model." (PMID 21190566, 2010). "Surprisingly, Mmp8-deficient mice displayed significantly higher severity of arthritis than Mmp8+/+ and Mmp8+/- mice (P = 0.025 by repeated-measures one-way ANCOVA test) all through the follow-up." (PMID 21190566, 2010). "Mmp8 deficiency increased the severity of arthritis, although the incidence of disease was similar in control and deficient mice." (PMID 21190566, 2010). "To explore the mechanisms underlying the increased arthritis severity in Mmp8-deficient mice, we used a genome-wide microarray analysis including probes for more than 28,000 mouse transcripts." (PMID 21190566, 2010). "To ascertain the role of MMP-8 in experimental arthritis, we induced passive K/BxN arthritis in 12-generation B6-backrossed Mmp8-deficient (Mmp8-/-) mice, and their matched wildtype (Mmp8+/+) and heterozygous (Mmp8+/-) littermate controls." (PMID 21190566, 2010). "Notably, some dermal DEGs (Tnfsf11, Ctsk, Mmp3, Mmp8, etc.)were associated with osteoclast differentiation and activation, which is linked to arthritis." (PMID 40471688, 2025). "The MMP8 gene encodes a proteolytic enzyme involved in the cleavage of the extracellular matrix in the proliferation and remodeling of tissues, embryonic development, as well as in pathological processes such as arthritis and metastasis." (PMID 33664351, 2021). "Arthritis was induced in Mmp8-deficient and wildtype mice by K/BxN serum transfer." (PMID 21190566, 2010). "The identification of S100A9, S100A8, and MMP8 genes can provide new therapeutic targets for arthritis pain and affect the signaling pathway to play an anti-inflammatory role after the treatment of BoNT/A." (PMID 34803684, 2021). "We found that the mRNA expression levels of S100A9, S100A8, and MMP8 were significantly decreased after CFA-induced arthritis pain, while BoNT/A increased the expression changes of these genes." (PMID 34803684, 2021). "The results showed that the expression levels of S100A9, S100A8, and MMP8 in rats with arthritis pain were visibly lower than the Sham group." (PMID 34803684, 2021). "The lack of MMP8 is accompanied by synovial inflammation and bone erosion in mice arthritis model, indicating that MMP8 has a protective role in this disease." (PMID 23351916, 2013). "According to our data, we conclude that Mmp-8 has a protective role in arthritis derived from the ability of this metalloprotease to induce changes in a series of inflammatory mediators." (PMID 21190566, 2010). "The present study indicates that MMP-8 protects against inflammatory synovitis and bone erosion in the K/BxN serum-transfer arthritis model." (PMID 21190566, 2010). "This indicates that the modified genes specific of arthritis in the Mmp8-/- mice are very varied and difficult to group." (PMID 21190566, 2010). "The lack of any clearly defined functional class of genes specifically modified in arthritic Mmp8-/- mice made it impossible to focus on them to try to discern important factors in the differential arthritis phenotype." (PMID 21190566, 2010). "As the severity of arthritis was similar in Mmp8+/+ and Mmp8+/- mice, these mice were considered a unique control group (Mmp8+)." (PMID 21190566, 2010).
Arthritis (continued). "We decided to concentrate instead on the genes that, having a most clearly changed expression with arthritis, were also most differentially affected in Mmp8+/+ and Mmp8-/- mice." (PMID 21190566, 2010). "To elucidate the mechanisms behind arthritis aggravation in Mmp8-/- mice, we have investigated the gene expression profile in Mmp8-sufficient and Mmp8-deficient mice with and without arthritis using microarray technology." (PMID 21190566, 2010). "The aim of the present study was to investigate the role of Mmp-8 (collagenase-2) in an arthritis model." (PMID 21190566, 2010). "Otherwise, there are few previous studies on MMP-8 and arthritis." (PMID 40410839, 2025). "MMP8 function can be dual as it has an important role in osteogenic differentiation by degradation of the chondrogenic matrix, and also has a protective role in arthritis formation." (PMID 30621194, 2019). "The action of MMP-8 in the inflammatory process depends on the stimulus in different situations, and MMP-8 might have a promoting or protective function in arthritis pathogenesis." (PMID 28445942, 2017). "A lack of MMP-8 causes the aggravation of arthritis through promotion of inflammation by IL-1β and PTX3, inducing the maturation and activation of osteoclasts or enhancement of the inflammatory infiltrate by PROKR2 and IL-1β." (PMID 28445942, 2017). "The expression of MMP-8 involves in the breakdown of extracellular matrix in bony tissue development, reproduction, and tissue remodeling, including disease processes such as arthritis and metastasis." (PMID 28445942, 2017). "An incidence of 100% of arthritis was observed in Mmp8-/-, Mmp8+/+ or Mmp8+/- mice." (PMID 21190566, 2010). "In a first experimental group, male and female Mmp8+/+ (n = 10), Mmp8+/- (n = 10) and Mmp8-/- (n = 10) mice were injected intraperitoneally at day 0 and 2 with 200 μl K/BxN mice serum and monitored for signs of arthritis." (PMID 21190566, 2010). "Changes occurring following castration that were independent of testosterone included BALF levels of TNF-α and CXCL2, lung levels of MMP-8, TIMP-1, and C5a, and lung autoantigen expression as well as lung cellular infiltrates and arthritis severity." (PMID 38086040, 2024). "In the present study, we have investigated the impact of lack of Mmp8 in the K/BxN serum-transfer arthritis model." (PMID 21190566, 2010). "We have found that the absence of Mmp8 increased the severity of arthritis without noticeably affecting its time course, either at its onset or at its spontaneous remission." (PMID 21190566, 2010). "Ankle joints from three mice from each of the following groups were studied: Mmp8+/+ and Mmp8-/- mice with and without arthritis." (PMID 21190566, 2010). "Lack of Mmp-8 is accompanied by exacerbated synovial inflammation and bone erosion in the K/BxN serum-transfer arthritis model, indicating that this Mmp has a protective role in arthritis." (PMID 21190566, 2010). "In arthritis, lack of MMP-8 is accompanied by exacerbated joint inflammation and bone erosion, indicating that MMP-8 might have a protective role in arthritis." (PMID 28423488, 2017). "Our results showed an increased PTX3 expression in mice lacking Mmp8 compared with wildtype mice, where it was also increased, indicating that PTX3 upregulation could have contributed to the higher arthritis severity in the knockout mice." (PMID 21190566, 2010).
chorioamnionitis (16 papers, 2010 to 2025). A morphologic finding indicating inflammation of the fetal sac membranes. "MMP8 is an enzyme neutrophil collagenase that has also been implicated in intra-amniotic infection and PTB." (PMID 40429621, 2025). "Intra-amniotic infection and preterm delivery are associated with high MMP-8 and MMP-9 concentrations in amniotic fluid and in the fetal membranes." (PMID 20868473, 2010). "It was suggested that MMP8-mediated inflammation of the chorion may be responsible for the lower birth weight as MMP8 was previously associated with chorioamnionitis and premature term delivery." (PMID 37445827, 2023). "Outside GDM, MMP-8 is associated with chorioamnionitis and preterm delivery." (PMID 32652973, 2020). "The positive detection of MMP-8 (>20 ng/mL) in amniotic fluid on a rapid bedside test is associated with a significantly higher rate of intra-amniotic inflammation, proven amniotic fluid infection and histological chorioamnionitis as well as shorter interval to delivery and neonatal morbidity." (PMID 38001923, 2023). "In ROC analysis, suPAR showed similarly good characteristics in diagnosing FIRS with histological chorioamnionitis, whereas MMP-8, TNF-α and IL-6 performed better in identifying FIRS alone." (PMID 38200448, 2024). "We compared the ability of suPAR to identify FIRS and FIRS with histological chorioamnionitis with that of other inflammatory biomarkers, such as MMP-8, TNF-α, and IL-6." (PMID 38200448, 2024). "Many other studies have also demonstrated that an increased level of MMP-8 in amniotic fluid is closely related to intra-amniotic infections, and concentrations of higher than 23 ng/mL have high prognostic values for intra-amniotic inflammations/infections." (PMID 33800521, 2021). "In our study, we found that the MMP-8 test had better specificity than the IL-6 test for the detection of chorioamnionitis." (PMID 33800521, 2021). "Our findings, as well as those presented in previous reports, support the use of IL-6, TNF-α, and MMP-8 analyses for the identification of chorioamnionitis in patients presenting with PPROM." (PMID 33800521, 2021). "Matrix metalloproteinase 8 (MMP-8), a more recent inflammatory marker, is related to intra-amniotic infection and cervical ripening, but MMP-8 activity seems also to be increased in patients with GDM." (PMID 32652973, 2020). "Lower GA and histologic chorioamnionitis were independent predictors of increased cord blood levels of IL-17 and/or MMP-8, respectively." (PMID 31001484, 2019). "S100a8, S100a9, Il1b, and Mmp8 have been strongly associated with fetal inflammatory response syndrome (FIRS), preterm labor, and chorioamnionitis in preterm infants, further supporting our rat model using IA LPS injections to simulate IAI and a FIRS-like response." (PMID 38481391, 2023). "Furthermore, amniotic fluid MMP-8 concentration is correlated with the severity of acute chorioamnionitis." (PMID 38001923, 2023). "The strength of this study is that this is one of the largest reported studies that has sought to determine the cut-off levels for IL-6 and TNF-α, and it is the first study to determine a cut-off level for MMP-8 in vaginally obtained amniotic fluid for the prediction of chorioamnionitis." (PMID 33800521, 2021). "Interestingly, we noted that the MMP‐8 cut‐off for FIRS was similar to that for histologic chorioamnionitis (MMP‐8: 170.76 vs. 172.53 ng/ml, respectively) although the TNF‐α cut‐off was four‐fold higher for FIRS than for histologic chorioamnionitis (TNF‐α: 89.20 vs. 21.17 pg/ml, respectively)." (PMID 36151969, 2023). "The optimum cut-off values for the prediction of chorioamnionitis were found to be 1389.82 pg/mL for IL-6, 21.17 pg/mL for TNF-α, and 172.53 ng/mL for MMP-8." (PMID 33800521, 2021). "The MMP-8 and TNF-α analyses can improve the prediction of chorioamnionitis, which is a contraindication to the expectant management and can lead to expedited delivery." (PMID 33800521, 2021).
chorioamnionitis (continued). "Vaginally obtained amniotic fluids with IL-6, MMP-8, and TNF-α seem to be good predictors for chorioamnionitis in patients with preterm premature rupture of the membranes before 34 weeks of gestation." (PMID 33800521, 2021). "The vaginally obtained amniotic fluid IL-6, MMP-8, and TNF-α seem to be good predictors for chorioamnionitis of patients with preterm premature rupture of membranes before 34 weeks of gestation." (PMID 33800521, 2021). "Unexpectedly, we did not establish any EGF association with histological chorioamnionitis, FIRS, or inflammatory cytokines such as IL-6, TNF-α, and MMP-8." (PMID 35328399, 2022). "In our research, we found that women with chorioamnionitis had higher vaginal fluid MMP-8 concentrations than women without this complication, and the cut-off value of 172.53 ng/mL had a particularly good diagnostic value." (PMID 33800521, 2021). "However, all the samples were obtained using the same technique, and the values of IL-6, TNF-α, and MMP-8 were statistically higher in the chorioamnionitis group than in the noninfection group." (PMID 33800521, 2021). "In contrast, the suPAR AUC was not significantly different from that of MMP-8 and IL-6 for identifying FIRS with histological chorioamnionitis." (PMID 38200448, 2024).
lung carcinoma (16 papers, 2008 to 2026). "In lung cancer, MMP8 is believed to be associated with a decreased lung cancer risk, and its profile was distinctly different according to histological types and patient recurrence status." (PMID 33816503, 2021). "Our results suggest that the studied polymorphism in the promoter region of the MMP8 gene is associated with lung cancer risk." (PMID 19094243, 2008). "Contrary to results observed for polymorphisms in MMP1 and MMP13, the polymorphism studied in MMP8 was associated with a reduced individual susceptibility to develop lung cancer in our study." (PMID 19094243, 2008). "This study suggests that the polymorphism in MMP8 is associated with a decreased lung cancer risk, which can be used as a prognostic marker in lung cancer." (PMID 19094243, 2008). "Our data suggest that individual carriers of the allele G in MMP8 had lower susceptibility to develop lung cancer, possibly due to the ability of collagenase-2 to induce anti-metastatic processes." (PMID 19094243, 2008). "Finally, it has been found that certain MMP8 mutations are correlated with risk of developing lung cancer." (PMID 30704450, 2019). "Serum TIMP-1 levels were significantly higher in individuals with prevalent and incident cancer, including colorectal and lung cancer, whereas lower MMP-8 levels were observed in colorectal and prostate cancer." (PMID 42162053, 2026). "In the case of lung cancers, MMP8 level, and possibly also its effect, depend on the cancer subtype." (PMID 31514474, 2019). "On the other hand, MMP8 mRNA expression increased along other MMPs in aggressive lung cancer cell lines resistant to targeted chemotherapy." (PMID 31514474, 2019). "Three independent studies show that MMP8 reduces interstitial tumor fluid pressure, increases fluid flow in various murine tumors, namely lung cancer, soft tissue sarcoma and HNSCC, and enhances the efficacies of oncolytic virus therapy and liposomal drugs." (PMID 31514474, 2019). "We have investigated the association between three polymorphisms (-1607 1G/2G, +17 C/G and -77 A/G) in the human collagenases MMP1, MMP8 and MMP13 and the risk of development or progression of lung cancer." (PMID 19094243, 2008). "In this study we have investigated the effect of polymorphisms in the promoter regions of the three human collagenases (MMP1, MMP8 and MMP13) and the individual risk of developing lung cancer in a group of 501 cases and 510 controls." (PMID 19094243, 2008). "Subsequently, upon further scrutinizing the MMP-8 expression levels in both tumor and normal tissues, noteworthy variations were discovered across various tumor types, with particularly heightened expression evident in gastrointestinal tumor and lung cancer." (PMID 37464428, 2023). "In conclusion, this work represents the first study in which polymorphisms in this important group of MMPs (MMP1, MMP8 and MMP13) are analyzed together to understand their contribution to lung cancer development and the effect on disease progression and survival in the Caucasian population." (PMID 19094243, 2008). "In this study, we reasoned that polymorphisms in the regulatory regions of the three human collagenases (MMP1, MMP8 and MMP13), affecting the expression level of these genes, might influence the risk and survival of lung cancer patients." (PMID 19094243, 2008). "Cleavage of SPARC extracellular Ca2+ binding domain by MMP‐8 and MMP‐13 has been detected in the serum of patients with lung cancer, suggesting their presence also in vivo." (PMID 36346290, 2023). "In lung cancer, measuring MMP8 levels in bronchial washings had no value in terms of detection." (PMID 31514474, 2019).
liver fibrosis (15 papers, 2010 to 2024). "Progression of liver fibrosis is associated with decreased matrix degradation due to inhibition of matrix metalloproteases (mostly MMP-8 and MMP-13), which is the result of increased expression of their natural inhibitor TIMP-1, something observed in treated LX2 cells." (PMID 24637780, 2014). "The results indicate the effectiveness of this strategy, as the expression of MMP-8 in a distant area from the site of administration can decrease liver fibrosis." (PMID 37681859, 2023). "This is in accordance with a study demonstrating similar efficiency of pro-MMP8 and active MMP-8 sent directly to the liver, to reverse liver fibrosis utilizing Ad-Hepatitis B chimeric vectors." (PMID 37681859, 2023). "Diverse MMPs can degrade fibrillar-type collagen, as in liver fibrosis, but MMP-8, MMP-1, and MMP-13 have proven to display the main activity." (PMID 37681859, 2023). "The expression of membrane-bound MMP-14 by Ly6Chi monocytes and MoMFs was especially intriguing, as most studies emphasize the importance of secreted MMPs like MMP-8,−9,−12, and−13 in reducing liver fibrosis." (PMID 32296422, 2020). "MMP2, MMP8, and MMP9 have all been reported to be associated with the progression of liver fibrosis and cirrhosis." (PMID 33315911, 2020). "It is also noteworthy that delivering a truncated form of MMP-8 to the livers of rats with hepatic cirrhosis reduces hepatic fibrosis." (PMID 24828408, 2014). "Only the cirrhotic animals treated with therapeutical genes (Ad-delta-huPA+Ad-MMP-8) showed improvement in liver fibrosis." (PMID 20509929, 2010). "A single administration of Ad-delta-huPA plus Ad-MMP-8 is efficient to induce fibrosis regression and increase survival in experimental liver fibrosis." (PMID 20509929, 2010). "In conclusion, Wfdc21, Lcn2, Pglyrp1, and Mmp8 may be potential and novel neutrophil targets to decrease liver fibrosis." (PMID 39040848, 2024). "Similarly, Siller-Lopez and colleagues showed that treatment with human MMP-8 showed amelioration of liver fibrosis in a CCl4 treated bile-duct ligation (BDL) rat model of liver fibrosis." (PMID 33262757, 2020). "Over expression of MMP-1, MMP-8 and MMP-13 was shown to reduce the number of activated HSC and attenuate the hepatic fibrosis when transiently over expressed in the liver." (PMID 30679661, 2019). "As with MMP-8, overexpression of MMP-9 in the mouse liver (using an adenovirus vector) reduces liver fibrosis after carbon tetrachloride (CCl4) treatment." (PMID 28336942, 2017). "The safety in the application and the remarkable property of the muscle to take gene constructs up and express different types of proteins, led us to adapt this design for a secretory protein, matrix metalloproteinase-8 (MMP-8), through a model of experimental advanced liver fibrosis in rats." (PMID 37681859, 2023). "In a model of murine liver fibrosis induced by carbon tetrachloride (CCl4), administration of PRI-724 (the inhibitor of CBP/β-catenin interaction) accelerated the resolution of liver fibrosis accompanied by an increase in MMP-9, MMP-2, and MMP-8 levels in intrahepatic leukocytes." (PMID 30308992, 2018). "Moreover, to further determine whether pre-ADSC treatment could significantly ameliorate liver fibrosis, we detected the expression of profibrogenic genes such as tissue inhibitor of metalloproteinases-1 (TIMP-1), matrix metalloproteinase (MMP-8 and 9), col1, and α-SMA." (PMID 35986406, 2022).